RNU6-966P (RNA, U6 small nuclear 966, pseudogene)
Gene: Small nuclear RNA gene on chromosome 15 (44,973,558 to 44,973,661, forward strand). Ensembl gene ENSG00000252288.
Homologues: Orthologues: chimpanzee U6 (99% identical), macaque U6 (96% identical), pig U6 (85% identical), rat LOC120097304 (83% identical), rabbit U6 (73% identical), guinea pig U6 (71% identical). Paralogues in human: RNU6-15P (89% identical), RNU6-16P (88% identical), RNU6-1 (88% identical), RNU6-166P (88% identical), RNU6-2 (88% identical), RNU6-25P (88% identical), RNU6-30P (88% identical), RNU6-3P (88% identical), RNU6-41P (88% identical), RNU6-44P (88% identical), RNU6-4P (88% identical), RNU6-574P (88% identical), and 1287 more.